POLR2D (RNA polymerase II subunit D)
Description:
Core component of RNA polymerase II (Pol II), a DNA-dependent RNA polymerase which synthesizes mRNA precursors and many functional non-coding RNAs using the four ribonucleoside triphosphates as substrates. Pol II is the central component of the basal RNA polymerase II transcription machinery. It is composed of mobile elements that move relative to each other. POLR2D/RPB4 is part of a subcomplex with POLR2G/RPB7 that binds to a pocket formed by POLR2A/RPB1, POLR2B/RPB2 and POLR2F/RPABC2 at the base of the clamp element. The POLR2D/RPB4-POLR2G/RPB7 subcomplex seems to lock the clamp via POLR2G/RPB7 in the closed conformation thus preventing double-stranded DNA to enter the active site cleft. The POLR2D/RPB4-POLR2G/RPB7 subcomplex binds single-stranded DNA and RNA.
Synonyms: RPB16; RPB4; HSRBP4; HSRPB4; RBP4
Tractability: Small molecule: a structure with a bound ligand is known. PROTAC: ubiquitination databases record sites on it; its protein half-life has been measured.
Gene: Protein-coding gene on chromosome 2 (127,843,553 to 127,858,155, reverse strand). Ensembl gene ENSG00000144231.
Subcellular location: Nucleus
Subcellular location (Human Protein Atlas): Nuclear speckles; Nucleoplasm; Cytosol
Pathways (Reactome):
Disease: Abortive elongation of HIV-1 transcript in the absence of Tat; Dengue Virus-Host Interactions; Formation of HIV elongation complex in the absence of HIV Tat; Formation of HIV-1 elongation complex containing HIV-1 Tat; Formation of the HIV-1 Early Elongation Complex; HIV Transcription Initiation; HIV elongation arrest and recovery; Pausing and recovery of HIV elongation; Pausing and recovery of Tat-mediated HIV elongation; RNA Pol II CTD phosphorylation and interaction with CE during HIV infection; RNA Polymerase II HIV Promoter Escape; Signaling by FGFR2 IIIa TM; Tat-mediated HIV elongation arrest and recovery; Tat-mediated elongation of the HIV-1 transcript; Transcription of the HIV genome; Viral Messenger RNA Synthesis
Gene expression (Transcription): Formation of RNA Pol II elongation complex; Formation of the Early Elongation Complex; MicroRNA (miRNA) biogenesis; PIWI-interacting RNA (piRNA) biogenesis; RNA Pol II CTD phosphorylation and interaction with CE; RNA Polymerase II Pre-transcription Events; RNA Polymerase II Promoter Escape; RNA Polymerase II Transcription Elongation; RNA Polymerase II Transcription Initiation; RNA Polymerase II Transcription Initiation And Promoter Clearance; RNA Polymerase II Transcription Pre-Initiation And Promoter Opening; RNA polymerase II transcribes snRNA genes; Transcriptional regulation by small RNAs
Metabolism of RNA: Processing of Capped Intron-Containing Pre-mRNA; mRNA Capping; mRNA Polyadenylation; mRNA Splicing - Major Pathway; mRNA Splicing - Minor Pathway
DNA Repair: Dual incision in TC-NER; Formation of TC-NER Pre-Incision Complex; Gap-filling DNA repair synthesis and ligation in TC-NER; Transcription-Coupled Nucleotide Excision Repair (TC-NER)
Developmental Biology: Activation of anterior HOX genes in hindbrain development during early embryogenesis
and 4 more pathways
Gene Ontology:
Molecular function: protein binding; translation initiation factor binding; nucleotide binding
Biological process: transcription by RNA polymerase II; transcription elongation by RNA polymerase II; transcription initiation at RNA polymerase II promoter; DNA-templated transcription initiation
Cellular component: nuclear speck; nucleoplasm; nucleus; RNA polymerase II, core complex; RNA polymerase complex
Genetic constraint (gnomAD): Loss-of-function variants: 8 observed, 8.98 expected, observed/expected ratio (o/e) 0.89, 90% interval 0.52 to 1.58. That is too few expected variants to judge how well the gene tolerates losing a copy. Missense variants: 80 observed, 105.4 expected, observed/expected ratio (o/e) 0.76, 90% interval 0.63 to 0.91. Synonymous variants: 33 observed, 33.25 expected, observed/expected ratio (o/e) 0.99, 90% interval 0.75 to 1.33.
Homologues: Orthologues: chimpanzee POLR2D (100% identical), dog POLR2D (100% identical), mouse Polr2d (100% identical), pig POLR2D (100% identical), rat Polr2d (100% identical), macaque POLR2D (99% identical), guinea pig POLR2D (99% identical), zebrafish polr2d (92% identical), tropical clawed frog polr2d (91% identical), Drosophila melanogaster Polr2D (72% identical), Caenorhabditis elegans rpb-4 (58% identical).
Diseases named in the same sentence as POLR2D in open-access papers:
POLR2D is named in the same sentence as 23 diseases in open-access papers, as found by Europe PMC text mining. Sharing a sentence is not in itself a finding about the gene and the disease. The quoted sentences say what the papers report.
colorectal cancer (1 paper, 2011). A primary or metastatic malignant neoplasm that affects the colon or rectum. "The cohort-dependent associations between overall survival and both Polr2d and Igf2bp3 have been observed in colorectal cancer and glioblastoma, respectively." (PMID 21649900, 2011).
prostate carcinoma (1 paper, 2022). A carcinoma that arises from epithelial cells of the prostate gland. "POLR2D is also known as DNA-directed RNA polymerase II, which was associated with shorter disease-free survival in prostate cancer." (PMID 35769257, 2022).
cancer (9 papers, 2015 to 2025). A tumor composed of atypical neoplastic, often pleomorphic cells that invade other tissues. "As to the transcription-related genes (coding for polymerase II subunits), the POLR2D gene was significantly hypomethylated not only in carcinomas (across almost all gene regions, except for 3′UTRs), but also in BOT.V600E (proximal promoter) compared to BOT (GR file)." (PMID 39456618, 2024). "AIDA, CETN3, FYB1 and POLR2D are also unfavourable prognostic markers across multiple cancer types." (PMID 32635403, 2020). "In our analysis, 6 out of 18 genes (EIF4A3, RAN, PSMA3, CCNA2, POLR2D, CDC27) were scored as SL hits against RB1 in at least two human cancer cell lines screens." (PMID 33591981, 2021). "In the pan-cancer cohort, comprising 505 tumors the promoter regions with the most significant FM bias comprise a shortlist of interesting candidate drivers, such as those of TERT, SYF2, ARGHEF18, and POLR2D." (PMID 27311963, 2016). "In contrast, our results showed that POLR2D was a protective factor for the OS in HGSOC patients, and this difference may attribute to the fact that the same gene may play different roles in the occurrence and development of different cancers." (PMID 35769257, 2022).
tumour (1 paper, 2020). "Significantly higher transcript levels were observed in GBM tumours for AIDA (2.5-fold, p = 3.4 × 10−8), BNIP3L (1.2-fold, p = 5.5 × 10−6), CETN3 (1.8-fold, p = 1.7 × 10−7), FYB1 (1.8-fold, p = 7.25 × 10−9) and POLR2D (1.7-fold, p = 8.14 × 10−5)." (PMID 32635403, 2020). "Interestingly, AIDA, BNIP3L, CETN3, FYB1 and POLR2D were specific to GBM plasma-EV, and correspondingly, significantly higher gene expression levels were observed in GBM tumour tissue relative to healthy brain." (PMID 32635403, 2020).
POLR2D also shares sentences with these, for which no sentence is quoted: Insulin resistance (2 papers); acne (1); amoebiasis (1); atherosclerosis (1); colon cancer (1); congenital night blindness (1); diabetes (1); glioblastoma (1); infection (1); Leber congenital amaurosis (1); lung carcinoma (1); melanoma (1); Nephropathy (1); non-small cell lung carcinoma (1); ovarian carcinoma (1); retinal degeneration (1); retinitis pigmentosa (1); retinopathy (1); vitamin A deficiency (1).